PARP1 (poly(ADP-ribose) polymerase 1)
Diseases named in the same sentence as PARP1 in open-access papers (continued):
Sharing a sentence is not in itself a finding about the gene and the disease.
tumor (continued). "Consistent with lower tumor PARP-1 levels, and consistent with lower in vitro uptake of 18F-olaparib, intravenous administration resulted in lower average uptake of 18F-olaparib in these tumors (2.59 ± 0.32 %ID/g), although this was not statistically significant." (PMID 30389822, 2019). "PARP1 is a key cellular regulator with increasingly recognized critical roles in cellular energetics and death signaling, allowing activity of this protein to serve as a switch between cell fates and to affect both tumor proliferation and therapeutic response." (PMID 31551501, 2019). "The down regulated proteins were associated with genome instability (plasmamix Histon H3 (diMeth K9), Histone H3), the regulation of tumour growth (Androgen receptor, beta-catenin, Bim, Shh), DNA repair (PARP-1) and Notch signaling (Notch 1 intracellular domain (N1ICD), RBPSUH)." (PMID 31758038, 2019). "By monitoring macroH2A1.1 levels in patient biopsy specimens, we may be able to better target PARP inhibitors to those tumors where PARP1 plays a key role in tumor cell survival." (PMID 31636161, 2019). "Our results agree with the observations that MCM2, MLH1 and ERCC1 may serve as an oncogene and that PARP1 may function as tumor suppressors genes during tumorigenesis." (PMID 31598158, 2019). "In addition, PARP1 promotes tumour growth by supporting the focal inflammation during the tumour progression." (PMID 30991935, 2019). "Therefore, PARP1 is expressed in olaparib-resistant tumours and sufficient olaparib concentrations can be achieved in resistant tumours to suppress its PARylation activity." (PMID 31080552, 2019). "On the whole, these studies indicate that elevated PARP-1 protein occurs in many tumor types suggesting an involvement in the oncogenic process, and may have prognostic value." (PMID 31877876, 2019). "To investigate whether the PARP1 p.T910A mutation provided a mechanistic explanation for the secondary failure of olaparib treatment, thereby validating PARP1 as a therapeutic target in this tumor, we performed protein structure modeling analyses." (PMID 30967556, 2019). "It appears that the rescuing effect of NOX inhibition or depletion may manifest when tumor growth is more drastically inhibited by PARP1 inhibition or depletion." (PMID 29684820, 2018). "In FFPE tissue samples both WEE1 and PARP1 showed a nuclear staining pattern in tumor cells." (PMID 29489886, 2018). "Together, these results confirmed that tumor hyperacetylation caused apoptosis through a RAGE-mediated signaling pathway initiated by binding of Ac-APE1/Ref-1 and alteration of Bcl-2 expression, leading to caspase activation and PARP-1 cleavage." (PMID 29880821, 2018). "Probe can quantify PARP‐1 expression in tumor cells and occupancy of PARP‐1 by olaparib." (PMID 29528513, 2018). "We next assessed whether PARP1 mutations could cause PARPi resistance in a clinically relevant setting, such as in BRCA1 mutant tumour cells." (PMID 29748565, 2018). "Indeed, western blotting showed that, in the tumor tissue, PARP1, Ku80, and Ku70 are located in high molecular weight regions of SEC." (PMID 30271949, 2018). "Combined, these studies indicate that elevated PARP‐1 occurs in many tumor types, and may have prognostic value." (PMID 30467127, 2018). "Moreover, we investigated the effect of CNTD2 overexpression on three markers of apoptosis (cleaved PARP1, Bax and caspase 9) in resected tumours." (PMID 30087414, 2018). "Anyhow, we believe a lot of the positive impact that might result from the introduction of the BRCA1/2 tumor testing, particularly because more patients should benefit from anti-PARP-1 targeted therapies or other similar new drugs coming soon." (PMID 29731958, 2018).
tumor (continued). "Based on our in vitro findings where RAPTA-T could lead to PARP-1 inhibition, we determined how tumor derived PAR levels correlated with vascular pericyte coverage by immunohistochemistry in vivo." (PMID 29980753, 2018). "Additionally, we have shown that hypoxia can lead to decreased HRR in vitro leading to an acquired “BRCAness” which translated into increased sensitivity to PARP-1 inhibition in hypoxic tumour cells." (PMID 29152107, 2017). "Consequently, PARP1 enables to compensate the impaired DNA repair and the tumor cells can survive and progress despite of their presence of DNA damage." (PMID 29212245, 2017). "PARP-1 inhibitors are of specific interest because they target the DNA repair pathway and they may also have an effect on the tumor vasculature." (PMID 29152107, 2017). "We found that administration of SB225002 in mice could significantly reduce PARP-1-promoted invading of tumor cells to liver after IR injury." (PMID 29179487, 2017). "Accordingly, PARP1 inhibitors may inhibit tumor progression via recovering the tumor suppressing function of related factors." (PMID 28991194, 2017). "Our group has previously shown that BIN1, originally identified as a MYC-interacting tumor suppressor, functions as a cellular inhibitor of PARP1 in vitro and that MYC induces cisplatin resistance by liberating intrinsic PARP1 activity through directly suppressing BIN1 levels." (PMID 28590415, 2017). "Therefore, we performed an integrated bioinformatic analysis to evaluate PARP1's genetic signature, and prognostic role regarding the molecular diversity of the tumour." (PMID 28654422, 2017). "In addition, several reports revealed the importance of PARP1 for EwS tumor development and progression." (PMID 28160567, 2017). "Additionally, multiple preclinical research studies and clinical trials demonstrate that inhibition of PARP1 can repress tumor growth and metastasis." (PMID 28991194, 2017). "In addition, immunohistochemistry studies on clinical human epithelial ovarian tumor samples found that PARP1 was significantly associated with microvascular density (MVD, CD34), tumor volume, and lymphatic metastasis." (PMID 28991194, 2017). "Nuclear PARP1 (nPARP1) expression was assessed in 263/308 (85.4%) of tumor samples." (PMID 29029467, 2017). "Because of that, the related information about the development of tumor could be obtained through the detection of PARP1 expression in blood at the early stage of NSCLC tumor." (PMID 29152079, 2017). "We hypothesized that PARP1 targeting could perpetuate trabectedin-induced DNA damage in tumor cells leading finally to cell death." (PMID 28454547, 2017). "Earlier reports indicate the involvement of PARP1 hyperactivation in cisplatin resistance in other tumor types.To determine the effect of olaparib on PARP1 activity, CC cells were treated with cisplatin along with two different concentrations (5 μM and 10 μM) of olaparib." (PMID 28993682, 2017). "PARP1 inhibition potentiated trabectedin activity in a PARP1-dependent manner and PARP1 expression in tumor cells might be a useful predictive biomarker that deserves clinical evaluation." (PMID 28454547, 2017). "Finally, the CDK12 inhibitor dinaciclib in combination with the PARP1/2 inhibitor veliparib resulted in inhibition of tumor growth in vitro, in vivo and in a patient-derived xenograft model." (PMID 29090014, 2017).
tumor (continued). "Small animal PET/CT experiments comparing MDA-MB-231 (low PARP-1 expressing) and MDA-MB-468 (high PARP-1 expressing) xenograft tumours revealed PARP-1 mediated tumour uptake which could be blocked following pre-injection of either Olaparib or [19F]FTT." (PMID 28058462, 2017). "In HR-proficient tumours, synthetic lethality can also be induced by combining PARP1-i with a local treatment of mild hyperthermia, which causes degradation of BRCA2 for several hours and thereby HR deficiency at the heated tumour site." (PMID 28427225, 2017). "According to the hepatic lesion alterations embodied in serum hepatic enzymes at different reperfusion time, we chose the hepatic repair phase (reperfusion time point: 12h) for further studies to elucidate the role of PARP-1 up-regulation during warm IR in tumor recurrence." (PMID 29179487, 2017). "An important question is whether Lig3, Lig1, or PARP1 inhibition could block tumor development, an area of our ongoing studies." (PMID 29238067, 2017). "In vivo, tumours were treated with any combination of PARP1-i, HT and cDDP to test whether the therapy induces similar effects in vivo as in vitro." (PMID 28427225, 2017). "DNA2, along with PARP1 inhibition, may be considered as a potential target for inducing synthetic lethality, a concept of killing tumor cells by targeting two essential genes." (PMID 28718810, 2017). "As RNF144A affects PARP1 protein abundance, we further demonstrated that the expression levels of RNF144A are associated with cellular sensitivity to olaparib in MDA-MB-231 cells in vitro and xenograft mouse tumor models." (PMID 29212245, 2017). "PARP1 inhibition by Olaparib, compared to the control, substantially reduced the tumor size and tumor load, albeit had no statistically significant impact on tumor number was observed in the tumor-laden Apcmin716/+ mice." (PMID 27458801, 2016). "This might be due to elevated PARP1 expression in a subset of tumor cells that were expressing low levels of PARP1 before treatment, but could also be a response of the tumor to the irradiation, and resulting immune cell recruitment." (PMID 26808835, 2016). "On histological tumor sections, the treatment resulted in an increase of PARP1 expression similar to that seen using flow cytometry in vitro (1.5 ± 0.4 fold increase in fluorescence/nucleus in treated versus untreated FaDu xenografts 48 hours post irradiation)." (PMID 26808835, 2016). "Since decrease in PARP1 expression is at the origin of both senescence and neoplastic emergence, PARP1 could be viewed as both a tumor promoter and a tumor-suppressor gene." (PMID 26822533, 2016). "In contrast to this when a tumor has highly expressing PARP-1, it might protect the tumor from the DNA damaging treatment effects." (PMID 27746584, 2016). "For all samples, tumor tissue could be detected by PARP1 expression with a specificity of 0.972 and a sensitivity of 0.974." (PMID 26900125, 2016). "Next, we determined whether FaDu and Cal27 tumors accumulated PARPi-FL after intravenous injection, and if tumor uptake was due to binding to PARP1." (PMID 26900125, 2016). "BRCA2 siRNA + olaparib treatment decreased both the number and weight of tumors relative to BRCA2 siRNA or olaparib treatment alone (p<0.05), suggesting that combing BRCA2 reduction with PARP1 inhibition may be useful to decrease tumor burden." (PMID 26959114, 2016). "Notably, olaparib-induced radiosensitisation was shown to be replication dependent, suggesting that the effects of PARP-1 inhibition would have greater effect in rapidly proliferating tumour cells." (PMID 27515310, 2016).
tumor (continued). "PARP1, for example, does not show genetic loss in tumours but does display a markedly low mRNA level in a number of patient tumor samples." (PMID 26781748, 2016). "Ultimately, the increase in PARP1 expression in individual nuclei, paired with higher nuclear densities after irradiation, could also be detected using ex vivo whole tumor imaging after PARPi-FL administration." (PMID 26808835, 2016). "PARP1 has been known to play an important role in tumor development in breast, ovary, and skin." (PMID 26540566, 2015). "Thus, the tumor cells were treated with PM and cleavage of PARP-1 was determined by western blotting." (PMID 25997419, 2015). "Taken together, PARP-1 overexpression in AML possibly caused by DNA damage which were associated with excessive division and proliferation of tumor cells may activate MPL." (PMID 26314963, 2015). "This discrepant observation raises a possibility that the oncogenic expression of PARP1 may lead to concomitant expression of FOXO3A as a compensatory mechanism to suppress tumor progression." (PMID 26540566, 2015). "Furthermore, PARP-1 up-regulates vimentin expression in aggressive metastatic melanomas, promoting an endothelial to mesenchymal transition, tumor angiogenesis, and distant metastases." (PMID 26314963, 2015). "Kaplan-Meier analyses also revealed that these features (i.e., tumor stage, PARP1, and FOXO3A) could predict prognostic outcomes of OS and RFS, respectively (log-rank test, P < 0.001)." (PMID 26540566, 2015). "In addition, preventing DNA repair through inhibition of PARP1/2 sensitizes tumor cells to radiotherapy and cytotoxic drugs that damage DNA, establishing a rationale for using PARP inhibitors as anticancer agents in combination therapy." (PMID 26513298, 2015). "Therefore, PARP-1 inhibition alleviated AML tumor load in vivo in mice and prolonged their survival." (PMID 26314963, 2015). "Moreover, co-treatment with CQ and BA145 enhanced the cleavage of procaspase-3 and PARP-1 in tumor tissues." (PMID 25608686, 2015). "Modification of any of these pathways/proteins through PARP1 inhibition could in theory affect tumor growth." (PMID 25984718, 2015). "In addition, FOXO3A was suggested as a downstream target for the tumor-suppressive effect of PARP1 inhibitor." (PMID 26540566, 2015). "PARP1 was found to co-regulatethe NF-kB activity and lead to increased secretion of pro-metastatic cytokines.The NF-kB signaling cascade is known to be essential for tumor growth." (PMID 26483957, 2015). "Whether the cell cycle arrest leads to the induction of apoptosis was investigated by measuring the binding of Annexin V-FITC and cleavage of PARP-1 in tumor cells treated with PM." (PMID 25997419, 2015). "There are various mechanisms of the pro-tumor activity of PARP1." (PMID 26483957, 2015). "E7449 is a novel, potent inhibitor of the DNA repair proteins PARP1 and 2; it traps PARP onto DNA to augment cytotoxicity and, comparable to earlier PARP inhibitors it exhibits selectivity for tumor cells that are deficient in HR repair and other DNA repair pathway proteins." (PMID 26513298, 2015). "Furthermore, dorsal window chamber and real time tumor vessel perfusion analyses in PARP-1-/- mice indicate a potential role for PARP in dilation of tumor-recruited vessels." (PMID 25689628, 2015). "PARP-1, a nuclear protein involved in DNA repair, is usually overexpressed in tumor tissue." (PMID 26314963, 2015). "Thus, inhibition of PARP-1 can sensitize tumor cells to classes of DNA damaging drugs that induce lesions subject to the BER repair pathway such as temozolomide, cyclophosphamide, camptothecin, etc.." (PMID 24970803, 2014). "PARP-1 variant genotypes may possibly be tissue specific because of high or low PARP-1 expression levels in different tumor tissues." (PMID 24853559, 2014).
tumor (continued). "Inhibition of PARP1 enhances sensitivity to radiation in various tumor types including those of lung, ovary, and prostate; PARP inhibition in conjunction with radiation treatment could be effective in these cancers." (PMID 24784564, 2014). "PARP1 can act in both a pro- and anti-tumor manner depending on the context." (PMID 25200342, 2014). "However, there is a major limitation because serum starvation and hypoxia (mimicking tumor microenvironments in-vivo) inhibit GEM-induced PARP-1 degradation by reducing autophagic activity." (PMID 25271986, 2014). "However, only PARP-1 mRNA in tumor significantly exceeded that in normal tissue (p = 0.00006), for OGG1 the differences were statistically insignificant (p = 0.24)." (PMID 25526641, 2014). "In addition, the assay for PARP1 cleavage confirmed the robust apoptotic response observed in the tumor derived CRCs versus the patient-matched normal CRCs from the same patient." (PMID 24742967, 2014). "In clinical studies, inhibitors of PARP-1 have been shown to selectively eliminate tumor cells." (PMID 24504413, 2014). "BMN 673, a novel PARP1/2 inhibitor in clinical development with substantial tumor cytotoxicity, forms extensive hydrogen-bonding and π-stacking in the nicotinamide pocket, with its unique disubstituted scaffold extending towards the less conserved edges of the pocket." (PMID 25195882, 2014). "Additionally, enhanced PARP-1 expression is seen in many tumor types compared to normal cells, and represents one of the mechanisms by which tumors avoid apoptosis caused by DNA damaging agents." (PMID 24624093, 2014). "More specifically, interacting partners of PARP-1 responsible for its recruitment and/or activation on TET1 gene may be deregulated in specific tumor cell lines thus affecting PARP-1 positive regulation of TET1 transcription." (PMID 24939750, 2014). "Data obtained in vitro were comparable to those obtained in vivo, in fact, Western blot analysis of H2596 (sarcomatoid MMe), MSTO-211H (biphasic MMe), REN (epithelioid MMe) and HMCs (human mesothelial) cells revealed an increase in PARP1 expression and auto-modification related to tumour histotype." (PMID 23301673, 2013). "However, since PARP1 also controls chromatin structure to regulate transcription, the action of PARP1 inhibitors on tumor cells is likely beyond its role for DNA damage response." (PMID 23921685, 2013). "Indeed, chemical inhibition of PARP-1 activity induced marked radiosensitization of several exponentially growing tumor cell lines in the 5–30 cGy dose range." (PMID 23565244, 2013). "The expression level of the PARP1 gene was also correlated with tumor grade." (PMID 24392019, 2013). "(iii) Tumor-promoting secretome: PARPi-mediated suppression of the role of PARP-1 in elaborating tumor-promoting secretome containing cytokines and growth factors has been suggested as a cause for decreasing the resistance to another mitotic inhibitor docetaxel." (PMID 24294592, 2013). "Furthermore, our findings suggest that PARP-1 inhibitors would be useful in a new therapeutic strategy that specifically targets Ets-1-expressing tumours." (PMID 23405229, 2013). "In this study, we highlight emerging information about the inhibition of PARP-1 in anthraquinone-derived derivatives outcomes, its interplay with antitumor activity against in the full panel of human tumor cell lines and the inhibition of these derivatives upon PARP-1." (PMID 23451039, 2013). "Furthermore, assays are being developed to analyze the activity of PARP1 inhibitors in peripheral blood cells as a potential surrogate for tumor biopsies." (PMID 23761859, 2013). "The effects of PARP-1 on ERK signaling are further enhanced by PARP-1-mediated transcription of vimentin, an intermediary angiogenic filament upregulated in tumor vasculature and pivotal for the endothelial-to-mesenchymal transition characteristic of metastasis." (PMID 24350055, 2013).